GALNT11 (polypeptide N-acetylgalactosaminyltransferase 11)
Description:
Polypeptide N-acetylgalactosaminyltransferase that catalyzes the initiation of protein O-linked glycosylation and is involved in left/right asymmetry by mediating O-glycosylation of NOTCH1. O-glycosylation of NOTCH1 promotes activation of NOTCH1, modulating the balance between motile and immotile (sensory) cilia at the left-right organiser (LRO). Polypeptide N-acetylgalactosaminyltransferases catalyze the transfer of an N-acetyl-D-galactosamine residue to a serine or threonine residue on the protein receptor. Displays the same enzyme activity toward MUC1, MUC4, and EA2 than GALNT1. Not involved in glycosylation of erythropoietin (EPO).
Synonyms: GalNAc-T11; GALNACT11
Tractability: Antibody: UniProt predicts a signal peptide or a membrane-spanning region.
Gene: Protein-coding gene on chromosome 7 (152,025,626 to 152,122,347, forward strand). Ensembl gene ENSG00000178234.
Subcellular location: Golgi apparatus membrane
Subcellular location (Human Protein Atlas): Endoplasmic reticulum; Golgi apparatus; Plasma membrane; Basal body; Cytokinetic bridge; Primary cilium; Primary cilium tip
Pathways (Reactome):
Metabolism of proteins: O-linked glycosylation of mucins
Gene Ontology:
Molecular function: Notch binding; polypeptide N-acetylgalactosaminyltransferase activity
Biological process: cilium assembly; determination of left/right symmetry; Notch receptor processing; Notch signaling involved in heart development; protein O-linked glycosylation; protein O-linked glycosylation via N-acetyl-galactosamine; regulation of Notch signaling pathway
Cellular component: Golgi apparatus; Golgi membrane
Genetic constraint (gnomAD): Loss-of-function variants: 45 observed, 71.09 expected, observed/expected ratio (o/e) 0.63, 90% interval 0.5 to 0.81. The upper end of that interval is the gene's LOEUF score, 0.81, which puts it in group 3 of 6, group 1 being the genes least tolerant of losing a copy. Missense variants: 666 observed, 801.26 expected, observed/expected ratio (o/e) 0.83, 90% interval 0.78 to 0.89. Synonymous variants: 268 observed, 295.87 expected, observed/expected ratio (o/e) 0.91, 90% interval 0.82 to 1.
Homologues: Orthologues: chimpanzee GALNT11 (99% identical), macaque GALNT11 (98% identical), rabbit GALNT11 (93% identical), dog GALNT11 (93% identical), guinea pig GALNT11 (91% identical), pig GALNT11 (91% identical), rat Galnt11 (89% identical), mouse Galnt11 (88% identical), tropical clawed frog galnt11 (73% identical), Drosophila melanogaster Pgant9 (39% identical), Caenorhabditis elegans gly-5 (37% identical), Drosophila melanogaster Pgant5 (36% identical), and 10 more. Paralogues in human: GALNTL5 (38% identical), GALNT1 (37% identical), GALNT13 (37% identical), GALNT6 (37% identical), GALNT2 (36% identical), GALNT14 (35% identical), GALNT3 (35% identical), GALNT16 (35% identical), GALNT4 (34% identical), GALNT5 (33% identical), GALNTL6 (33% identical), GALNT10 (33% identical), and 7 more.
Diseases named in the same sentence as GALNT11 in open-access papers:
GALNT11 is named in the same sentence as 12 diseases in open-access papers, as found by Europe PMC text mining. Sharing a sentence is not in itself a finding about the gene and the disease. The quoted sentences say what the papers report.
chronic lymphocytic leukemia (3 papers, 2014 to 2016). "Of these genes, Galnt11 is of particular interest, as it has recently been shown to be up-regulated in chronic lymphocytic leukemia (CLL) and associated with poor disease prognosis." (PMID 25544807, 2014). "Many essential glycosylated proteins, such as Notch, are altered in malignant cells, and the recent finding of GALNT11 as a new molecular marker in Notch-mediated chronic lymphocyte leukemia (CLL) has increased interest in understanding Notch glycosylation." (PMID 26925390, 2016). "In a recent report on chronic lymphocytic leukemia (CLL), a low density of Tn residues and higher expression of GALNT11 was observed in B-CLL cells and healthy T-cells suggesting that GalNAcT11 contributes to B- and T lymphocyte differentiation and transformation." (PMID 27322213, 2016).
chronic kidney disease (2 papers, 2021 to 2024). Impairment of the renal function secondary to chronic kidney damage persisting for three or more months. "Since the role of megalin in renal reabsorption of vitamin D has been elucidated, this similarity in bone phenotype associated with Galnt11-deficiency and chronic kidney disease hints at the possibility of a shared mechanism." (PMID 38484798, 2024). "Genome-wide association studies have previously reported an association between GALNT11 and chronic kidney disease." (PMID 38484798, 2024). "Genetic abnormalities associated with the deficit of glycosyltransferase Galnt11 has been associated with chronic kidney disease." (PMID 34827620, 2021). "The findings of increased trabecular bone volume and decreased cortical bone volume among Galnt11-deficient mice resembles what has been previously documented in individuals with renal osteodystrophy, a common complication associated with chronic kidney disease." (PMID 38484798, 2024).
Autoimmunity (1 paper, 2009). The occurrence of an immune reaction against the organism's own cells or tissues. "Our study supports this body of evidence but also extends the findings to propose new candidates governing autoimmunity that are implicated in glycosylation (Pomgnt1, Galnt11 and Galnt10)." (PMID 19915720, 2009).
leukemia (1 paper, 2023). A malignant (clonal) hematologic disorder, involving hematopoietic stem cells and characterized by the presence of primitive or atypical myeloid or lymphoid cells in the bone marrow and the blood. "Inc.reased GALNT11 expression has been reported for leukemia, and KMT2C has been associated with tumorigenesis." (PMID 38137484, 2023).
respiratory depression (1 paper, 2020). A decrease in ventilation secondary to impaired signals from the central nervous system. "Mapping these traits in the DO mice and evaluation of sequence variants and protein structure, followed by integrative functional genomic analysis in GeneWeaver, has allowed us to implicate Galnt11 as a candidate gene for respiratory depression in response to morphine." (PMID 32917924, 2020).
secondary hyperparathyroidism (1 paper, 2024). Overproduction of parathyroid hormone in response to influence external to the parathyroid glands. "Moreover, we demonstrate effects on the bones of Galnt11-deficient animals that are consistent with secondary hyperparathyroidism." (PMID 38484798, 2024).
situs inversus (1 paper, 2019). A congenital condition in which there is complete right-to-left reversal of the position of the major thoracic and abdominal organs (that is, they are arranged in a mirror image of the normal positioning). "GALNT11 might contribute to the phenotype of situs inversus in KTS." (PMID 31507630, 2019).
tumor (2 papers, 2022 to 2025). "Single-cell RNA sequencing analysis further revealed that NOTCH signaling components, such as GALNT11, HES1, KIT, and SLC35C1, are significantly upregulated in tumor-associated monocytes/macrophages." (PMID 40361382, 2025). "LGALS1, B4GALT6, and GALNT11 were upregulated and MGAT5, MAN1A1, MANBA, LUM, GALNT1 and 7, HAPLN3, and ST6GALNAC5 were downregulated in Fra-2 cl 1 select primary tumours, while MGAT4A was upregulated." (PMID 34693476, 2022).
GALNT11 also shares sentences with these, for which no sentence is quoted: congenital heart disease (1 paper); intellectual impairments (1); osteomalacia (1); renal osteodystrophy (1).